RN7SL862P (RNA, 7SL, cytoplasmic 862, pseudogene)
Gene: Miscellaneous RNA gene on chromosome 18 (9,830,330 to 9,830,627, reverse strand). Ensembl gene ENSG00000242651.
Homologues: Orthologues: chimpanzee Metazoa_SRP (97% identical), macaque Metazoa_SRP (91% identical). Paralogues in human: RN7SL1 (81% identical), RN7SL2 (81% identical), RN7SL3 (81% identical), RN7SL45P (80% identical), RN7SL769P (80% identical), RN7SL91P (80% identical), RN7SL126P (80% identical), RN7SL444P (80% identical), RN7SL650P (80% identical), RN7SL197P (79% identical), RN7SL322P (79% identical), RN7SL709P (78% identical), and 703 more.